APOE (apolipoprotein E)
Diseases named in the same sentence as APOE in open-access papers (continued):
Sharing a sentence is not in itself a finding about the gene and the disease.
atherosclerosis (continued). "Furthermore, KIAA1363/ApoE double knockout mice showed accelerated development of atherosclerosis, as evident by increased aortic surface areas covered by atherosclerotic lesions accompanied with increased cholesterol ester content." (PMID 35101424, 2022). "Subsequently, we confirmed in vivo that QHZYF could attenuate atherosclerosis in ApoE−/− mice and regulate the expression levels of related molecules in PPARγ/LXRα/ABCA1-ABCG1 and PPARγ/NF-κB p65 pathways of ApoE−/− mice and C57BL/6 wild-type mice." (PMID 36518993, 2022). "We showed this mechanism was highly relevant in two in vivo murine models not usually associated with thrombosis: established atherosclerosis in ApoE-/- mice fed a high fat diet and cutaneous delayed type hypersensitivity (DTH)." (PMID 36172348, 2022). "Moreover, given the role of Nox5 in diabetic complications and because atherosclerosis is accelerated in diabetes, we further induced diabetes in some of the eNOX5ki/ki x ApoE−/− mice by the injection of low-dose streptozotocin (STZ)." (PMID 35798762, 2022). "Similarly, our investigation of diabetic atherosclerosis of ApoE−/− mice revealed the enhanced expression level of NLRP3-ASC and GSDMD in the atherosclerotic plaques of endothelial cells with aortic sinus." (PMID 36425580, 2022). "Furthermore, vascular peroxidase 1 has been suggested as having a role in the regulation of lipid homeostasis and the development of atherosclerosis, by mediating ApoE oxidation and impairing plasma lipid clearance." (PMID 35174233, 2022). "On the other hand, complete (whole-body) knockout of Scarb1 increases atherosclerosis in apoE−/− mice (Scarb1−/−, apoE−/−) as a result of impaired RCT, and humans who are homozygous for a rare loss-of-function mutation of Scarb1 are 1.8 times more likely to develop coronary heart disease." (PMID 35464770, 2022). "APOE can downregulate M1 phenotype macrophage markers and upregulate markers of anti-inflammatory M2 macrophages via surface APOE receptors in the development of atherosclerosis." (PMID 35669791, 2022). "Endothelium-specific Txndc5 deletion markedly reduced atherosclerosis in ApoE−/− mice." (PMID 35061532, 2022). "Notably, APOE modulates brain glucose metabolism in AD, and affects glucose uptake in atherosclerosis." (PMID 35090515, 2022). "Furthermore, in ApoE‐/‐ mice model of C. pneumoniae infection-induced atherosclerosis, the expressions of JunB, Fra-1 and MMP2 in VSMCs in atherosclerotic lesions were also increased compared with mock infected ApoE‐/‐ mice." (PMID 35493076, 2022). "However, there were studies that demonstrated the protective role of IL-33 in atherosclerosis, where the development of atherosclerosis was significantly reduced in ApoE−/− mice administered with IL-33 through Th1-to-Th2 switching." (PMID 36552551, 2022). "In this study, we compared atherosclerosis and associated phenotypes in scavenger receptor class B type I knockout mice with those of wild type, LDL receptor knockout, and apolipoprotein E knockout mice after 20 weeks of being fed an atherogenic diet containing sodium cholate." (PMID 36714321, 2022). "Moreover, some XO inhibitors, such as febuxostat, can prevent the development of atherosclerosis in ApoE-KO mice." (PMID 35047104, 2022). "Under normal diet, APOE -/- mice develop atherosclerosis, gradually worsening over the lifespan." (PMID 35921269, 2022). "The present study used a model of ApoE−/− C57BL/6 mice in which pristane administration resulted in SLE combined with atherosclerosis, presenting reduced spontaneous activity, marked alopecia, splenomegaly, and significantly higher levels of ANA and anti-dsDNA, in agreement with previous reports." (PMID 35571092, 2022).
atherosclerosis (continued). "It is tempting to speculate that effects of this Affibody on atherosclerosis in ApoE-/- mice may be discrepant between segments in the arterial tree, but the sample size here is too limited and further studies are needed." (PMID 35282365, 2022). "Apolipoprotein E knockout (ApoE−/−) mice is a classic model for atherosclerosis research." (PMID 36145277, 2022). "Since MDSCs aggravated atherosclerosis in SLE in ApoE−/−Fas−/− mice, we intend to explore whether deletion of MDSCs alleviate disease in ApoE−/−Fas−/− mice." (PMID 35850768, 2022). "A relatively new method in rabbits to study atherosclerosis is the ApoE−/− model." (PMID 35760040, 2022). "In conclusion, STZ-induced T2D accelerates the progression of atherosclerosis in ApoE-/- mice." (PMID 36286043, 2022). "The divergence in the microbial composition in the ApoE WD group was corresponded to severe atherosclerotic lesion areas in the aortic root, further indicating the diet-dependent effects of the gut microbiota on atherosclerosis." (PMID 35256637, 2022). "In sharp contrast, a deletion of the NLRP3 inflammasome component in Apoprotein E–deficient (ApoE−/−) mice had no significant impact on atherosclerosis." (PMID 35641492, 2022). "Furthermore, A2Kb-Tg ApoE–/– mice immunized with P210-PAM had significantly reduced aortic atherosclerosis compared with mice injected with PBS." (PMID 35536648, 2022). "ApoE−/− mice are fed a high-fat diet for 8 weeks to induce atherosclerosis." (PMID 35145192, 2022). "In this study, we used SRC-3-/-ApoE-/- mice to assess the role of SRC-3 in atherosclerosis." (PMID 36263184, 2022). "Similar to APOE-4, apolipoprotein J, apolipoprotein E are significant predictors of Alzheimer’s disease and may play a role in the pathogenesis of atherosclerosis." (PMID 36291661, 2022). "The effects of lycopene on this specific pathway in the context of atherosclerosis are not yet fully described; therefore, the aim of this study was to analyze the effects of a lycopene extract from Sicilian cherry tomatoes on atherosclerosis development in ApoE KO mice fed with HFD." (PMID 35883529, 2022). "On the other hand, the area of the atherosclerosis was significantly smaller in ApoE−/−; Neu-Pad4−/−mice fed with a HFD than in ApoE−/−mice, regardless of whether the nicotine was administered or not." (PMID 35923856, 2022). "Additionally, studies have also pointed towards possible transmission of obesity, IBD and other conditions including susceptibility to atherosclerosis via TMAO and endotoxemia in ApoE-knockout mice." (PMID 36556351, 2022). "Increased macrophage FABP4 expression is linked to atherosclerosis, and co-treatment of statins and Dex, but not Dex alone, exacerbated high-fat diet-induced atherosclerosis in apoE-deficient mice." (PMID 36054185, 2022). "As atherosclerosis in mice is intimately linked to plasma cholesterol levels, we measured those and observed a ~2-fold elevation in plasma cholesterol in Western-B6+DOP-treated ApoE−/− mice compared to the Western group both after 6 and 12 weeks of treatment." (PMID 36077004, 2022). "Our previous study had demonstrated that an antibody may reduce atherosclerosis by activating monocyte/macrophage polarization in ApoE−/− mice." (PMID 36233020, 2022). "Importantly, betaine intervention can lower the increased plasma levels of SAH and reduce atherosclerosis in ApoE−/−/SAHH+/− mice." (PMID 35277077, 2022).
atherosclerosis (continued). "Therefore, un-charged expression of hepcidin at any stage of atherosclerosis progression in ApoE–/– mice cannot be considered as evidence denying the role of increased iron contents in the aortic tissues in ApoE deficiency-induced atherosclerosis in mice." (PMID 35669479, 2022). "In ApoE−/− mice with atherosclerosis, PMSN specifically accumulated in atherosclerotic plaques." (PMID 35118420, 2022). "Additionally, in vivo viral overexpression of GRP119 in ApoE–/– mice fed high-fat diets shows that it has a protective effect against atherosclerosis by increasing cholesterol efflux and reducing the expression of proinflammatory cytokines." (PMID 36082127, 2022). "Moreover, nanoparticles formulated to deliver Txndc5-targeting CRISPR-Cas9 plasmids driven by an endothelium-specific promoter (CDH5) significantly increase eNOS protein and reduce atherosclerosis in ApoE−/− mice." (PMID 35061532, 2022). "Interestingly, treatment with CXCL10 neutralizing antibody reduced the size and stability of atherosclerotic plaques in the carotid cuff model of atherosclerosis in ApoE–/– mice." (PMID 36247423, 2022). "Platelets from apoE−/− mice deficient in platelet‐specific junction adhesion molecule A, an inhibitor of integrin αIIbβ3 outside‐in signaling, released more CXCL14, suggesting an important role for this chemokine in vascular inflammation and atherosclerosis." (PMID 36250653, 2022). "ApoE−/−/SOD2+/− mice showed increased atherosclerosis and plaque vulnerability." (PMID 35883899, 2022). "Furthermore, in another study geniposide was able to protect against atherosclerosis and inhibited the formation of foam cells by regulating the equilibrium of expression of diverse lipid transporters in ApoE-knockout mice." (PMID 35408655, 2022). "In addition, Tregs were also shown to promote protection from atherosclerosis in apolipoprotein E knockout mice." (PMID 35428200, 2022). "Given the immune-regulating effects of IFNγ-B cells, we subsequently assessed whether adoptive transfer of these IFNγ-B cells was able to reduce collar-induced atherosclerosis in apoE−/− mice." (PMID 35187121, 2022). "Therefore, the mono-selective, new generation RIPK1 kinase inhibitor GSK’547 was included in the present study to treat atherosclerotic ApoE−/− Fbn1C1039G+/− mice, which is a model of advanced, human-like atherosclerosis." (PMID 35625752, 2022). "Apolipoprotein E knockout (ApoE-/-) mice are more mature models of atherosclerosis." (PMID 35178108, 2022). "We recently identified a high-affinity C1q-ApoE complex in human artery atherosclerotic intima lesions and in human amyloid plaques of Alzheimer’s Disease brains defining a common pathogenetic pathway of two diverse diseases, i.e. atherosclerosis and dementia." (PMID 36304458, 2022). "Compared with ApoE−/− mice, ApoE/NOS3−/− mice showed more severe atherosclerosis, suggesting that hypertension may aggravate the process of atherosclerosis, and the underlying mechanism needs to be studied further." (PMID 36360235, 2022). "Another key regulator of cell proliferation and apoptosis during atherosclerosis preventing its development is lincRNA-p21, whose expression was dramatically downregulated in atherosclerotic plaques of ApoE -/-mice, leading to promoted cell proliferation and repressed apoptosis in VSMCs." (PMID 35563540, 2022).
atherosclerosis (continued). "Moreover, ApoE–/– mice is widely used in the basic research for atherosclerosis because of their ability to display pathological features of human atherosclerosis." (PMID 35845572, 2022). "In an ApoE−/− high-fat diet murine model of atherosclerosis, delivery of a small molecule CCR2 antagonist showed significant decrease in plaque size and lesional macrophage numbers only in mice treated at ZT17 but not when the same antagonist was applied at ZT5." (PMID 36339576, 2022). "However, ApoE−/− mouse models of atherosclerosis have generated some controversy around the role of the NLRP3 inflammasome." (PMID 36459456, 2022). "Chronic exposure to BaP accelerated the atherosclerosis process in apoE-knockout mice." (PMID 35739584, 2022). "In this study, we found that global SRC-3 deficiency or endothelial SRC-3 knockdown on an ApoE-/- background ameliorated the development of atherosclerosis, suggesting that SRC-3 could promote atherosclerosis development." (PMID 36263184, 2022). "Loss of FGF21 accelerates the plaque formation and the development of atherosclerosis in apoE KO mice, and administration with recombinant human FGF21 protein strongly attenuates the development of atherosclerosis in apoE KO mice by suppression of cholesterol synthesis and production of adiponectin." (PMID 35463746, 2022). "Currently, ApoE knockout (ApoE-KO; ApoE−/−) mice are commonly used to study human atherosclerosis; however, they lack the typical symptoms of hypertension and poorly mimic human hypertension-induced atherosclerosis." (PMID 36360235, 2022). "The results thus far provide evidence that P210-PAM immunization provokes a response that modulates T cell function and macrophage phenotypes and reduces atherosclerosis in ApoE–/– mice, supporting the feasibility of the immunogenic nanoparticle approach to reduce atherosclerosis." (PMID 35536648, 2022). "Additionally, lycopene decreased cholesterol absorption in the intestine and prevented atherosclerosis progression in a well-studied atherosclerosis model, which involved apolipoprotein E knockout (ApoE−/−) mice fed with HFD." (PMID 35883529, 2022). "Similarly, when challenged with constant light exposure, ApoE-/-mice exhibit exacerbated dyslipidemia and atherosclerosis." (PMID 35966094, 2022). "ApoE/NOS3−/− mice had more severe hepatic steatosis and atherosclerosis than ApoE−/− mice." (PMID 36360235, 2022). "Besides or in combination with the antiatherogenic and antioxidative properties of apoA‐IV, recombinant apoA‐IV stabilises the atherosclerosis plaque in the apoE‐knockout C57BL/6 mice and prevents acute plaque disruption." (PMID 34914850, 2022). "Our findings suggest that the incorporation of hyperglycemia with hyperlipidemia and atherosclerosis could exacerbate ARHL in ApoE KO male mice." (PMID 36408520, 2022). "EEEG significantly alleviated atherosclerosis in ApoE−/− mice fed a high-fat diet for 16 weeks." (PMID 36505350, 2022). "The potential of IL-1β manipulation in atherosclerosis has been known for years, since ApoE−/−/IL-1β−/− mice exhibited significant decreases in aortic sinus atherosclerotic lesions and adhesion molecules expression compared to ApoE−/− only mice." (PMID 36555579, 2022). "Consistently, GPX4 overexpression in ApoE−/− mice was shown to protect against atherosclerosis." (PMID 36192693, 2022).
atherosclerosis (continued). "In the present study, to clarify whether the combination of PD and PSP would have great effects on atherosclerosis, transgenic ApoE–/– mice model of atherosclerosis induced by HFD were used." (PMID 35845572, 2022). "High-cholesterol diet induces atherosclerosis in A2Kb-Tg ApoE–/– mice." (PMID 35536648, 2022). "In addition, ApoE−/− mice were used in the present study due to their advantages in simulating hyperlipidemia and atherosclerosis, which are two of the most common characteristics of “phlegm-damp” syndrome in patients with CVDs." (PMID 35350989, 2022). "The APOE−/− mice spontaneously exhibited atherosclerosis after the 3-month HCD diet." (PMID 35565954, 2022). "ApoE−/− mice under HFD were used as an animal model of atherosclerosis." (PMID 36142173, 2022). "Furthermore mtDNA damage promotes atherosclerosis in ApoE−/− mice with defective mtDNA polymerase proof-reading activity and is associated with features of plaque vulnerability." (PMID 36497101, 2022). "Moreover, functional blockage of CD147 ameliorated atherosclerosis in ApoE (-/-) mice by downregulating MMP activity." (PMID 35096272, 2022). "Therefore, ApoE–/– mice are not only used in the study of atherosclerosis but are also used as a new animal model in the study of the mechanism of cognitive impairment." (PMID 36188475, 2022). "ApoE−/− mice are widely used to establish experimental models of atherosclerosis." (PMID 36285165, 2022). "For example, irisin supplementation can significantly improve endothelial dysfunction, decrease endothelial apoptosis, and predominantly decrease atherosclerotic plaque area in nicotine or streptozotocin-induced apolipoprotein E-Null [apoE(−/−)] atherosclerosis mice." (PMID 36225200, 2022). "The HFD-fed ApoE-/- mice are a well-established model for studying atherosclerosis." (PMID 36286043, 2022). "In ApoE-/- mice fed a high-fat diet (HFD), endothelial loss of SIRT6 promotes monocyte adhesion to ECs, impairs endothelium-dependent vasorelaxation, and facilitates atherosclerosis development." (PMID 35855341, 2022). "In accordance with this, also in ApoE−/− mice with diabetes and atherosclerosis, dapagliflozin treatment reduces circulating levels of NLRP3, IL-1β, and IL-18, as well as in the abdominal aorta, which contributes to reducing the atherosclerotic lesions and to increasing its stability." (PMID 35628443, 2022). "Therefore, we investigated the effects of endurance exercise on atherosclerosis induced by a Western diet (WD) and apolipoprotein E (ApoE) knockout in terms of microbiota parameters and metabolites." (PMID 35256637, 2022). "Similar results were obtained in the apoE knockout mouse atherosclerosis model." (PMID 36551839, 2022). "ApoE−/− mice were given a high-fat diet to establish atherosclerosis (AS) model, and macrophages in mice were isolated and extracted to transfect Cx37 vectors with silencing or overexpressing, and Kv1.3 pathway blockers were used to inhibit the pathway activity." (PMID 36193415, 2022). "Interestingly, circulating ceramides derived from the intestine promote the development of atherosclerosis, and decreasing plasma ceramides through suppression of the intestinal FXR/Smpd3 axis reduced lesion areas in the aortas of ApoE-deficient mice." (PMID 35789435, 2022). "To determine whether the administration of recombinant IL-27 affects the progression of atherosclerosis, we treated ApoE−/− mice with IL-27/anti-IL-27p28 antibody/PBS for another 8 weeks after 8 weeks of western diet consumption." (PMID 36405994, 2022).